AGTR2 (angiotensin II receptor type 2)
Description:
Receptor for angiotensin II, a vasoconstricting peptide. Primarily signals via a non-canonical G protein- and beta-arrestin independent pathways. Cooperates with MTUS1 to inhibit ERK2 activation and cell proliferation.
Synonyms: AT2; MRX88; ATGR2
Tractability: Small molecule: a drug acting on it is in phase 2 or 3 trials; a structure with a bound ligand is known; a high-quality ligand is known; it belongs to a druggable protein family. Antibody: its Gene Ontology location is reachable by antibodies, with high confidence; UniProt places it where antibodies can reach, with medium confidence; UniProt predicts a signal peptide or a membrane-spanning region. PROTAC: a small molecule that binds it is known.
Target class: Membrane receptor; Angiotensin receptor; Peptide receptor (family A GPCR); Family A G protein-coupled receptor; Short peptide receptor (family A GPCR)
Chemical probes: Buloxibutid (high quality)
Safety:
Unwanted effects reported when the protein is acted on. In parentheses: how it was acted on, where the effect was seen, and who reports it.
cerebral complications (inhibition, developmental toxicity; renal; source: Lynch et al. (2017))
death (inhibition, developmental toxicity; renal; source: Lynch et al. (2017))
decreased blood pressure (inhibition, developmental toxicity; renal; source: Lynch et al. (2017))
decreased pain (inhibition, acute dosing; renal; source: Lynch et al. (2017))
hypocalvaria (inhibition, developmental toxicity; renal; source: Lynch et al. (2017))
increased urinary sodium excretion (activation, acute dosing; renal; source: Lynch et al. (2017))
increased urine excretion (activation, acute dosing; renal; source: Lynch et al. (2017))
intrauterine growth retardation (inhibition, developmental toxicity; renal; source: Lynch et al. (2017))
limb defects (inhibition, developmental toxicity; renal; source: Lynch et al. (2017))
oligoamnios (inhibition, developmental toxicity; renal; source: Lynch et al. (2017))
persistent patent ductus arteriosus (inhibition, developmental toxicity; renal; source: Lynch et al. (2017))
pulmonary hypoplasia (inhibition, developmental toxicity; renal; source: Lynch et al. (2017))
renal failure (inhibition, developmental toxicity; renal; source: Lynch et al. (2017))
respiratory distress syndrome (inhibition, developmental toxicity; renal; source: Lynch et al. (2017))
Gene: Protein-coding gene on chromosome X (116,170,744 to 116,174,974, forward strand). Ensembl gene ENSG00000180772.
Subcellular location: Cell membrane
Pathways (Reactome):
Signal Transduction: G alpha (i) signalling events; Peptide ligand-binding receptors
Gene Ontology:
Molecular function: angiotensin type II receptor activity; protein binding; receptor antagonist activity; G protein-coupled receptor activity
Biological process: cell surface receptor signaling pathway; negative regulation of neurotrophin TRK receptor signaling pathway; positive regulation of extrinsic apoptotic signaling pathway; vasodilation; blood vessel remodeling; brain development; G protein-coupled receptor signaling pathway; G protein-coupled receptor signaling pathway coupled to cGMP nucleotide second messenger; inflammatory response; negative regulation of blood vessel endothelial cell migration; negative regulation of cell growth; negative regulation of heart rate; nitric oxide-cGMP-mediated signaling; regulation of blood pressure; regulation of systemic arterial blood pressure by circulatory renin-angiotensin; angiotensin-activated signaling pathway; angiotensin-mediated vasodilation involved in regulation of systemic arterial blood pressure; blood vessel diameter maintenance; exploration behavior; positive regulation of branching involved in ureteric bud morphogenesis; positive regulation of DNA-templated transcription; positive regulation of metanephric glomerulus development; regulation of apoptotic process; regulation of metanephros size
Cellular component: plasma membrane; membrane
Gene-disease validity (ClinGen):
ClinGen rates the evidence that AGTR2 causes each of these diseases.
X-linked complex neurodevelopmental disorder (X-linked): Disputed. A complex neurodevelopmental disorder that is transmitted via X-linked inheritance, and is characterized by intellectual disability, autism and epilepsy.
Homologues: Orthologues: chimpanzee AGTR2 (99% identical), macaque AGTR2 (99% identical), dog AGTR2 (96% identical), pig AGTR2 (95% identical), rabbit AGTR2 (93% identical), rat Agtr2 (92% identical), mouse Agtr2 (92% identical), tropical clawed frog agtr2 (47% identical), zebrafish agtr2 (40% identical). Paralogues in human: AGTR1 (31% identical), BDKRB2 (28% identical), BDKRB1 (27% identical), APLNR (25% identical), GPR25 (25% identical), RXFP4 (25% identical), GPR15 (23% identical).
Diseases named in the same sentence as AGTR2 in open-access papers:
AGTR2 is named in the same sentence as 139 diseases in open-access papers, as found by Europe PMC text mining. Sharing a sentence is not in itself a finding about the gene and the disease. The quoted sentences say what the papers report.
Hypertension (38 papers, 2011 to 2025). The presence of chronic increased pressure in the systemic arterial system. "It is also worthy to note that the AGTR2:rs11091046 polymorphism has been previously found to be associated with several cardiovascular phenotypes such as acute myocardial infarction, hypertension or hypertrophic cardiomyopathy." (PMID 40428340, 2025). "Increased angiotensinogen (AGT) production by white adipose tissue has been related to both obesity and hypertension, and loss of Agtr2 expression is sufficient to rescue obesity induced by adipose tissue AGT overexpression." (PMID 35208177, 2022). "Increased Agtr2 expression in the female vasculature is implicated in the increased female-specific protection from hypertension, vascular injury, and renal function." (PMID 29259233, 2017). "As for AGTR2 gene rs1403543 SNP, significant associations were also reported for hypertension, and preeclampsia." (PMID 28792482, 2017). "Increased expression of Agtr2 in murine female vasculature is implicated in protection from hypertension and CVD32–34." (PMID 29259233, 2017). "Whereas AGTR2 hasn’t been a target for cancer drug development, it has been a successfully exploited target for the development of hypertension drugs." (PMID 25420785, 2014). "To further characterize the potential underlying causes of hypertension, hypertrophy, and fibrosis development in CKD, we measured the renal expressions of Kiss1 and Agtr2 genes as well as ACE activity and the serum levels of para-cresyl sulfate and indoxyl sulfate." (PMID 37987885, 2024). "A latest animal experiment showed that Roxadustat can alleviate hypertension and organ damage through upregulation of angiotensin receptor type 2 (AGTR2) and endothelial NO synthase (eNOS), downregulation of angiotensin receptor type 1 (AGTR1), and inhibition of oxidative stress." (PMID 35318873, 2022). "This investigation will provide basis for further analysis AGTR2 that might acts to ameliorate progression of renal injury and hypertension, and that this is an estrogen-dependent phenomenon." (PMID 25902787, 2015). "In summary, FG-4592 treatment remarkably ameliorated hypertension and organ injury, possibly through stabilizing HIF1α and subsequently targeting eNOS, AGTR1, AGTR2, and oxidative stress." (PMID 34403364, 2021). "For COVID-19 patients with existing hypertension, the key targets and drugs are losartan, saralasin, telmisartan for targets AGTR1, AGTR2, and captopril for ACE and REN." (PMID 34067609, 2021). "The renin-angiotensin system (RAS) has been known to be related to heart health and angiotensin II type 1 (AGTR1) and type 2 receptor (AGTR2) in the RAS possess unique counterregulatory function in blood pressure regulation, which is crucial for the prevention of hypertension and CVD." (PMID 28792482, 2017). "In addition, neither of the 2K1C-hypertension and treadmill exercises did affect the AGTR2 expression level in the hippocampus." (PMID 35628344, 2022). "In an angiotensin II (Ang II) hypertension model, FG-4592 abolished hypertensive responses; prevented vascular thickening, cardiac hypertrophy, and kidney injury; downregulated AGTR1 expression; and enhanced AGTR2, endothelial NO synthase (eNOS), and HIF1α protein levels in the aortas of mice." (PMID 34403364, 2021). "Given that Ace2 and Agtr2 are X-chromosome-located RAS genes, whether sex chromosomes influence their expression to protect females against HF-induced programmed hypertension deserves further clarification." (PMID 27462279, 2016).
cardiac hypertrophy (14 papers, 2012 to 2026). "Abating pressure overload by hydralazine, blockade of AT2 receptor with the AT2 antagonist PD123319 or deletion of AT2(Agtr2-/Y) prevents cardiac hypertrophy." (PMID 22558183, 2012). "However, diabetic female rats develop early subclinical myocardial deformation, cardiac hypertrophy via elevated expression of pro-hypertrophic miR-208a, myocardial damage, and suppression of cardio-reparative Angiotensin II receptor 2 (Agtr2)." (PMID 29259233, 2017). "We reported that increasing Agtr2 gene and AT2R protein expression by the AT2R-specific peptide ligand NP-6A4 in obese and diabetic male heart improves cardiac functions and cardiac capillary density and mitigates cardiac hypertrophy and fibrosis." (PMID 36909327, 2023).
Stroke (14 papers, 2012 to 2024). Sudden impairment of blood flow to a part of the brain due to occlusion or rupture of an artery to the brain. "Notably, analysis of 341 DE mRNA associated with stroke (259 upregulated, 82 downregulated) in the IR group revealed upregulation of genes like Ccl2, Cxcl1, C3, Serpine1, Adamts7, Csf3, Ptx3, MMP8, Lif, and Lcn2, and downregulation of Gdf10, Agtr2 and Shank3." (PMID 39170713, 2024). "Our RNA sequencing analysis revealed that gene expression of the angiotensin II type 2 receptor (AT2R), Agtr2, was downregulated in HT + Stroke compared to NT + Stroke." (PMID 38886874, 2024).
COVID-19 (10 papers, 2020 to 2025). A disease caused by infection with severe acute respiratory syndrome coronavirus 2. "The presence of the AGTR2 rs1403543-AA genotype was associated with a 3.8-fold increased risk of COVID-19 retinopathy (p = 0.05)." (PMID 35885894, 2022). "An increased risk of severe COVID-19 was also associated with an AGTR2 polymorphism (rs1914711)." (PMID 36835445, 2023). "One of the AGTR2 polymorphisms (rs1914711) was shown to increase the risk of severe COVID-19 in the Mayan population." (PMID 35885894, 2022). "It is noteworthy that ACE, ACE2, and AGTR2 polymorphisms have also been associated with hypertension, diabetes, coronary artery disease, and stroke, which complicates the risk estimation, as those comborbities alone are associated with an increased risk of COVID-19." (PMID 36835445, 2023). "Hence the AGTR2 rs1403543 AA genotype might represent a genetic risk factor for COVID-19 retinopathy in males." (PMID 35885894, 2022). "Nevertheless, our previous study, focusing on patients without known comorbidities, showed an increased risk of COVID-19 retinopathy in males with the AGTR2-AA genotype of the rs1403543 polymorphism." (PMID 36835445, 2023). "The disruption of signaling pathways via the AT2 (angiotensin II receptor type 2) and G proteins by the SARS-CoV-2-bound ACE2 complex cannot properly elucidate the severe and systemic effects of COVID-19." (PMID 36146578, 2022). "In this context, autoantibodies such as ACE2-aab, AGTR2-aab, BDKRB1-aab, CXCR3-aab, MAS1-aab, CHRM5-aab, NRP1-aab, F2R-aab, STAB1-aab appeared to play a major role in stratifying COVID-19 by disease burden." (PMID 35264564, 2022). "Compound 21 (C21) is the only AT2R agonist used in clinical trials for idiopathic pulmonary fibrosis and COVID-19, but not for heart disease, and there are no reports that show C21 increases Agtr2 gene expression." (PMID 37408206, 2023). "The less spoken about angiotensin II receptor type 2 (AT2R) has anti-inflammatory and anti-fibrotic effects in lung tissue and may be of significance in light of the lung pathology presentation in COVID-19." (PMID 32626626, 2020).
diabetes (10 papers, 2012 to 2023). "Further research is required to understand the full impact of KDT501's PPARγ and AGTR2-mediated mechanisms and their functional roles in diabetes." (PMID 24498211, 2014). "CYP1A1, HHIP (hedgehog interacting protein), AGTR2, CYP2A6, and PCK1 are involved in growth and development of diabetes mellitus." (PMID 38137330, 2023). "Attenuation of cardiac Agtr2 is a female- and diabetes-specific effect because healthy ZL-M displayed lower expression of cardiac Agtr2 compared with ZL-F and levels in ZDF-M were not lowered with diabetes." (PMID 29259233, 2017). "In Agtr2+/+ mice, diabetes induced a significant increase of the mesenteric artery media thickness whereas no change has been shown in Agtr2-/- mice between control and diabetic groups." (PMID 24511993, 2014).
Obesity (9 papers, 2012 to 2024). Accumulation of substantial excess body fat. "For instance, certain polymorphisms, such as AVP rs3729965 and AGTR2 C4599A, exhibit obesity-dependent risks." (PMID 39408215, 2024). "The elevations of RAS-related gene expression and RAS activation in the adipose tissues are associated with obesity; for example, Agtr1 and Agtr2 regulate adipogenesis." (PMID 37862361, 2023). "In the post-HCT group we found significantly lower expression of AGTR2, FLJ32810, NR3C2 and TMEM133 genes, and significantly higher expression of BAT2D1, MOV10, PIK3CG and WNK1 genes compared with the obesity control group." (PMID 33927307, 2021). "In the pre-HCT group we found significantly lower expression of AGTR2, BLK, FLJ32810 and TMEM133 genes, and significantly higher expression of MOV10 and WNK1 genes compared with the obesity control group." (PMID 33927307, 2021).
bladder cancer (5 papers, 2011 to 2025). "AGTR2 activation induced apoptosis in some cells or cell lines, such as neurons, bladder cancer cells, and PC12W cells." (PMID 35281029, 2022). "It needs to be determined if AGTR2 has a similar function in human bladder cancer cells." (PMID 22013484, 2011). "Of these, three hub genes involving angiotensin II receptor, type 2 (AGTR2), fibroblast growth factor 13 (FGF13), and lysophosphatidic acid (LPA) receptor 3 (LPAR3) (marked by red color) have been reported to participate in cell migration and angiogenesis in bladder cancer or lactotroph tumors." (PMID 31708963, 2019).
Cognitive impairment (5 papers, 2012 to 2023). Abnormal cognition is characterized by deficits in thinking, reasoning, or remembering. "Similarly, ACE inhibition can delay neurodegeneration via the retardation of tau hyperphosphorylation, while ACE2 and AGTR2 activation can protect against cognitive impairments." (PMID 37107585, 2023).
dementia (5 papers, 2012 to 2024). Loss of intellectual abilities interfering with an individual's social and occupational functions. "We have found that none of the analysed polymorphisms in the genes of renin-angiotensin system, i.e. rs699, rs4762 in AGT, rs5186 in AGTR1, rs5194, rs1403543 in AGTR2 or ACE I/D was associated with MCI or dementia in Parkinson’s disease." (PMID 34302265, 2021). "The gene expression of mediators of cRAS signaling, ACE1 and AGTR1, and AGTR2, calibrated to RGs, was unaltered in all 3 dementia subtypes." (PMID 37813091, 2024).
idiopathic pulmonary fibrosis (5 papers, 2008 to 2025). Idiopathic pulmonary fibrosis (IPF) is a nonneoplastic pulmonary disease that is characterized by the formation of scar tissue within the lungs in the absence of any known cause. "The tissue-specific angiotensin II receptor 2 (AGTR2) gene is expressed in lung fibrosis and is shown by our analysis to be highly regulated in the lung’s ventilation group." (PMID 35271646, 2022).
mental retardation (5 papers, 2008 to 2023). "They further screened AGTR2 mutations in 590 male patients with intellectual disability and identified one frameshift and three missense mutations of AGTR2 in 8 patients." (PMID 37511534, 2023). "Other studies further supported the association between AGTR2 mutations and intellectual disability." (PMID 37511534, 2023). "Also, a novel missense mutation of AGTR2 was identified in a Japanese male patient with severe intellectual disability, pervasive developmental disorder, and epilepsy." (PMID 37511534, 2023). "This hypothesis was further corroborated by two other studies reporting mutations of AGTR2 in patients suffering from intellectual disability, seizures, restlessness, hyperactivity, and disrupted speech development." (PMID 23320146, 2012). "Nevertheless, several other studies argued against the role of AGTR2 in intellectual disability." (PMID 37511534, 2023). "Hence, it remains unclear whether mutations in AGTR2 are associated or not with intellectual disability." (PMID 23320146, 2012). "In that study, the authors detected the absence of the expression of AGTR2 in a female patient with an intellectual disability who had a balanced translocation between X and seven chromosomes." (PMID 37511534, 2023).
preeclampsia (5 papers, 2017 to 2025). Preeclampsia is a hypertensive disorder of pregnancy that is characterized by new-onset hypertension with proteinuria presenting after 20 weeks of gestation, and depending on mild or severe forms may initially present with severe headache, visual disturbances, and hyperreflexia. "The AGTR2 C4599A polymorphism in mothers, fathers, and babies was linked to preeclampsia, but this association was evident only in pregnancies where the women had a BMI ≥ 25 kg/m2, indicating a gene–environment interaction." (PMID 39408215, 2024). "AGTR2 has been suggested to play arole in modulating uteroplacental circulation, and harbors variants that may contribute tothe risk of preeclampsia." (PMID 28877031, 2017).
heart failure (4 papers, 2013 to 2023). Inability of the heart to pump blood at an adequate rate to meet tissue metabolic requirements. "Studies had shown that CYP1A1 and AGTR2 are master regulators that are activated in heart failure." (PMID 38137330, 2023).
Insulin resistance (4 papers, 2012 to 2014). Increased resistance towards insulin, that is, diminished effectiveness of insulin in reducing blood glucose levels. "Recent reports show that pharmacological activation of a second KDT501 target, AGTR2, in combination with PPARγ activation, ameliorates insulin resistance and reverses β-cell damage in diabetic pancreatic tissue in T2D mice." (PMID 24498211, 2014).
left ventricular hypertrophy (4 papers, 2012 to 2025). Enlargement of the LEFT VENTRICLE of the heart. "There are some reports indicating an association of rs1403543 (1675G>A) polymorphism in the AGTR2 gene, which encodes the type-2 angiotensin II receptor, with left ventricular hypertrophy or increased left ventricular mass (LVM) in adults." (PMID 40428340, 2025).
type 2 diabetes (4 papers, 2012 to 2025). "MMP2 was associated with extracellular matrix (ECM) receptor interaction, and high AGTR2 expression correlated with Type II diabetes mellitus pathways." (PMID 40995593, 2025).
lung adenocarcinoma (3 papers, 2013 to 2020). A carcinoma that arises from the lung and is characterized by the presence of malignant glandular epithelial cells. "A previous research showed that AGTR2 was under-expressed in lung adenocarcinoma and played a role in the pathology of adenocarcinoma." (PMID 33072067, 2020).
ovarian carcinoma (3 papers, 2017 to 2024). A malignant neoplasm originating from the surface ovarian epithelium. "Activation of AGTR2 has been reported to reduce the effect of ANGII on ovarian cancer cell survival." (PMID 30845964, 2019).
prostate carcinoma (3 papers, 2011 to 2014). A carcinoma that arises from epithelial cells of the prostate gland. "AGTR2 expression has been associated with apoptosis in prostate cancer cells." (PMID 22013484, 2011).